TYMS (thymidylate synthetase)
Diseases named in the same sentence as TYMS in open-access papers (continued):
Sharing a sentence is not in itself a finding about the gene and the disease.
adenocarcinoma (6 papers, 2005 to 2017). A common cancer characterized by the presence of malignant glandular cells. "Overexpression of TYMS was also observed in both subtypes of adenocarcinoma compared to normal mucosa." (PMID 15655543, 2005). "In terms of OS, TYMS was not predictive for treatment while women, adenocarcinoma histology, early disease stage (for Subgroup C only) and taxanes/platinum combination were independently associated with prolonged survival." (PMID 22866924, 2012).
infection (6 papers, 2015 to 2024). The state of being infected such as from the introduction of a foreign agent such as serum, vaccine, antigenic substance or organism. "To obtain the optimal titer of lentiviral particles to inhibit cell proliferation by silencing TYMS expression we used increasing doses of both lentiviral TS shRNAs and NS shRNA (2 to 12 MOI) and performed MTS assay 72 h after infection." (PMID 37106126, 2023). "Furthermore, seven genes (CDK1, TYMS, MCM5, KIF11, CCNB2, MAD2L1, and MCM4) have been identified as core hub genes involved in cell-cycle regulation, potentially serving as mediators in the pathogenesis triggered by NN1172 infection within the thymus." (PMID 38362295, 2024).
gastrointestinal tumor (5 papers, 2008 to 2018). "This association can be biologically interesting as compared to the 2R genotype, the 3R genotype was previously associated with increased TYMS protein levels in colorectal/gastrointestinal tumor tissues." (PMID 29394274, 2018). "Recent studies showed that TYMS protein expression in gastrointestinal tumors was also associated with this polymorphism." (PMID 29088787, 2017). "TYMS, the gene that encodes thymidylate synthase, has been demonstrated to be an independent prognostic biomarker of patients that have undergone 5-fluorouracil chemotherapy for the treatment of gastrointestinal tumors." (PMID 24926347, 2014).
peripheral neuropathy (2 papers, 2013 to 2021). A disorder affecting the peripheral nervous system. "It is the first report on the association between TYMS rs11280056 and peripheral neuropathy." (PMID 35056973, 2021).
gastrointestinal disease (1 paper, 2021). A disease that occurs in the gastrointestinal system, excluding the hepatobiliary system. "Based on the Open Targets analysis, we found 76 gastrointestinal diseases related to TYMS, of which 27 diseases had a comprehensive score of 1 (score range of 0–1)." (PMID 34141464, 2021).
vasculopathy (1 paper, 2020). "Thus, our identified DEGs (RRM2, APC, CHEK1, E2F6, TYMS, E2F7, and CDK6) from the cluster 2 subnetwork are highly related to and consistent with the members of the signaling pathways associated with the immune system, apoptosis, the cell cycle, and vasculopathy." (PMID 32426333, 2020).
TYMS also shares sentences with these, for which no sentence is quoted: gastric tumor (6 papers); malignant pleural mesothelioma (6); malaria (5); breast adenocarcinoma (4); ischemic stroke (3); bladder cancer (2); head and neck squamous cell carcinoma (2); nasopharyngeal carcinoma (2); Non-Squamous Non-Small Cell Lung Cancer (2); oral squamous cell carcinoma (2); pleural mesothelioma (2); skin cancer (2); acute pancreatitis (1); alcoholic liver diseases (1); atherosclerosis (1); babesiosis (1); Barrett's metaplasia (1); bone cancer (1); brain tumors (1); Breast tumor (1); cardiomyopathy (1); cerebral infarction (1); cerebrovascular diseases (1); Chagas disease (1); cholangiocarcinoma (1); clear cell renal cell carcinoma (1); colon adenocarcinoma (1); colorectal adenoma (1); colorectal signet ring cell carcinoma (1); congenital heart disease (1).
A further 56 diseases each share a sentence with TYMS in 1 paper.